EZH2 (enhancer of zeste 2 polycomb repressive complex 2 subunit)
Diseases named in the same sentence as EZH2 in open-access papers (continued):
Sharing a sentence is not in itself a finding about the gene and the disease.
tumor (continued). "Interestingly, EZH2 is aberrantly overexpressed in a variety of neoplasms compared to normal tissues and is currently the subject of intense research for the better understanding of cancer biology." (PMID 27199994, 2016). "Furthermore, EZH2 promotes tumor cell migration and invasion via epigenetic repression of E-cadherin in renal cell carcinoma." (PMID 26623562, 2016). "Furthermore, tumor tissues formed by EZH2-overexpressing HeLa cells expressed much more EZH2 protein, stronger Ki67 staining and much more Ki67-positive cells." (PMID 27092879, 2016). "In addition, DNA double-strand break repair is prevented and tumor cells become more sensitive to ionizing radiation after EZH2 knockdown." (PMID 27259264, 2016). "Indeed, overexpressed EZH2 deregulates tumor cell proliferation by directly inducing CCND1 transcription." (PMID 26497210, 2016). "Blocking EZH2 expression or activity may represent a promising strategy for anti-cancer treatment targeting tumor cells, tumor endothelial cells and tumor stem cells." (PMID 26683709, 2016). "Our data suggest that concomitant administration of small molecule inhibitors of EZH2 may significantly increase the anti-tumor efficacy of conventional chemo- and radiotherapies in CRPC." (PMID 26657505, 2016). "We identified a significant positive correlation between EZH2 expression and cell proliferation in vitro and tumor formation in vivo by the up-regulation or down-regulation of EZH2 using CRISPR-Cas9-mediated gene editing technology and shRNA in HeLa and SiHa cells." (PMID 27092879, 2016). "EZH2 is an epigenetic regulatory protein associated with tumor aggressiveness and negative survival outcomes in several human cancers." (PMID 27793210, 2016). "Furthermore, in many types of cancer cells, EZH2 mediates cell proliferation, invasion and migration by epigenetically repressing tumor suppressor gene expressions through trimethylating H3K27." (PMID 27494834, 2016). "Emerging data support SWI/SNF as an epigenetic tumor suppressor and EZH2 as an oncogene." (PMID 27125524, 2016). "Furthermore, knockdown of lncRNA XIST exerts its tumor-suppressive effect though down-regulating the expression of EZH2 via miR-101." (PMID 27620004, 2016). "Furthermore, EZH2 protein, as a transcriptional repressor, may help the induction of transcriptional repression and participation in the controlling of gene expression patterns in the gastric epithelial cells, thereby resulting in the loss of tumour suppressor functions." (PMID 26859127, 2016). "Of interest, although applying EZH2 inhibitor, E7438 induces reproducible re-expression of crucial epithelial tumor suppressor genes (including CDH1) in 13 tested MM cell lines, there are many questions arising from a high variability in E7438 sensitivity in the proliferation assays." (PMID 27239242, 2016). "In the present study, we determined that EZH2 might be an oncogene that performs an important function in CRC tumor development." (PMID 27172794, 2016). "Increased EZH2 activity induces the genomewide histone H3 lysine 27 trimethylation (H3K27me3) and may act as an oncogene via the repression of tumor suppressor genes in human cancers." (PMID 26871294, 2016). "As EZH2 inhibitors are currently being tested in several clinical trials as anti-cancer drugs, novel important observations are anticipated to emerge about how these compounds also affect anti-tumor immune function." (PMID 27793053, 2016). "Although EZH2 inhibitors would provide an attractive treatment strategy in cancers with high EZH2 expression and activation, such approaches might have unpredictable effects on anti-tumor immunity." (PMID 27793053, 2016). "Furthermore, we demonstrated that combination of CPT treatment and shRNA-mediated knockdown of EZH2 resulted in much greater inhibition of C4-2 tumor xenograft growth in mice." (PMID 26657505, 2016).
tumor (continued). "We further examined EZH2 and p21 expression in the xenografted tumor tissues by IHC analysis." (PMID 27882937, 2016). "EZH2 was positively correlated with tumor stage (p = 0.027)." (PMID 27472460, 2016). "We also found that that the function of FOXF1-AS1 was related to EZH2 and it regulated the tumor biological behavior by targeting FOXF1, indicating that further investigation of FOXF1-AS1 might lead to the development of novel NSCLC therapies." (PMID 27577075, 2016). "Importantly, the functions of EZH2 in T effector and Treg cells appear to mediate distinct and opposing roles, in anti-tumor immunity." (PMID 27793053, 2016). "Because there was a strongly high association between the Ki67 proliferation index and EZH2 expression levels, we argue that EZH2 overexpression likely confers a proliferative advantage to EZH2-high cells which allows these tumor cells to escape cell cycle regulation." (PMID 27113214, 2016). "Although increased expression of EZH2 has been observed in aggressive solid tumors in humans, the mechanism involved in the mediation of tumor aggressiveness by EZH2 remains unclear." (PMID 27502594, 2016). "Moreover, overexpression of EZH2 indicates the tumor more aggressive and is related to poor prognosis." (PMID 27706111, 2016). "Because of the unequivocal negative impact of Treg localization in the tumor microenvironment on anti-tumor immunity the regulation of EZH2 expression in Tregs in tumor microenvironment is of particular interest for understanding and modulating anti-tumor immunity." (PMID 27793053, 2016). "In addition, EZH2 is demonstrated to dictate cell fate in response to DNA damage and combination of etoposide with EZH2 inhibitors elicits potent anti-tumor activity." (PMID 26973857, 2016). "Thus, the use of EZH2 inhibitors with the goal to inhibit tumor growth will likely simultaneously alter the functions of immune cells in the tumor microenvironment." (PMID 27793053, 2016). "Detection of this EZH2 network may serve as a promising biomarker for tumor progression into higher grade." (PMID 27793053, 2016). "Many reports show that EZH2 plays a central role in proliferation through both regulation of proteins involved in proliferation as well as downregulation of expression of several tumour suppressor genes." (PMID 26964089, 2016). "In our previous immunohistochemical research, we found that expression of the EZH2 was significantly higher in tumor tissues than the paired normal tissues, and EZH2 might facilitate tumorigenesis in CRC cells." (PMID 27706111, 2016). "As EZH2 is important for maintaining CCS-like cell properties in vitro, we further evaluated whether EZH2 is involved in vivo tumorigenicity using a tumor xenograft model." (PMID 27172794, 2016). "Furthermore, as nuclear staining of EZH2 can display single or small cluster of tumor cells embedded in stroma, it is useful in detecting micro-invasion of breast carcinoma in some cases." (PMID 27113214, 2016). "In addition, this study also showed that silencing EZH2 resulted in tumor growth inhibition, apoptosis, and chemosensitivity enhancement." (PMID 27223261, 2016). "This prompted us to investigate whether knockdown of lncRNA XIST exerted its tumor-suppressive effects through regulating of EZH2 expression." (PMID 27620004, 2016). "For example, in addition to promoting cell cycle progression, LINC00152 might promote tumor cell invasion and metastasis by repressing E-cadherin via EZH2 in GC." (PMID 26799422, 2016). "In contrast, inhibiting EZH2 reduces tumor invasion and angiogenesis." (PMID 27172794, 2016). "Interestingly, TNBC tumors were shown to have elevated levels of EZH2 but surprisingly low levels of H3K27me3 suggesting an HMT-independent role of EZH2 in this tumor subtype." (PMID 27764181, 2016).
tumor (continued). "Moreover, several studies have evaluated the role of EZH2 overexpression in NSCLC and demonstrated that high EZH2 expression is correlated with the early pathogenesis, tumor progression, poor prognosis and poor overall survival for patients with NSCLC." (PMID 27472460, 2016). "miR-26a was reported to suppress tumor growth by targeting EZH2 in some tumors." (PMID 26733151, 2016). "The contribution of hyperactive or hypoactive EZH2 during tumor formation may reflect the complex and important roles that EZH2-associated genes play in cell fate decisions." (PMID 27835578, 2016). "High expression of EZH2 in tumor tissues correlated with poor patient prognosis." (PMID 27172794, 2016). "Moreover, EZH2 has received attention as a target for cancer treatment because EZH2-mediated tri-methylation of histone H3K27 results in inactivation of tumor suppressor genes such as PSP94 and p16INK4a." (PMID 27340776, 2016). "EZH2 expression of different tumor grades displayed obvious difference (P < 0.05)." (PMID 26378043, 2015). "EZH2, one of the components of Polycomb group proteins (PRC2) complex, catalyzes the trimethylation of histone H3 lysine 27 that is associated with transcriptional repression and tumor development." (PMID 26268310, 2015). "More importantly, gain or loss function assays suggested that targeting MICU1 could compensate EZH2's effect on regulating tumor cell apoptosis." (PMID 26378043, 2015). "We, therefore, evaluated whether miR-101 is de-regulated in eRMS and investigated its interplaying with EZH2 as well as its role in the in vitro tumorigenic potential of these tumor cells." (PMID 26251675, 2015). "To that, miR-101 can behave as a tumor suppressor in several cancers by repressing EZH2 expression." (PMID 26251675, 2015). "Moreover, EZH2 regulates the self-renewal and differentiation of murine hepatic stem/progenitor cells and tumor-initiating HCC cells are highly dependent on EZH2 for their tumorigenic activity." (PMID 26062443, 2015). "Here, we identified a novel mechanism in which co-overexpression of Snail and Slug can recruit EZH2 by silencing of tumor-suppressive miR-101, thus establishing a functional link between aberrant expression of Snail and Slug and global down-regulation of miRNAs in OTSCC." (PMID 25762643, 2015). "In addition, it has been shown that EZH2 contributes to epidermal-mesenchymal transformation and angiogenesis, leading to an increased metastatic potential of tumor cells." (PMID 26593398, 2015). "Based on our observations, it can be hypothesized that low levels of miR-101 in eRMS contribute to the up-regulation of EZH2, which sustains tumor cell proliferation." (PMID 26251675, 2015). "Reduced expression of EZH2 could also notably increase tumor cell apoptosis and enhance sensitivity to cisplatin via decreasing H3K27me3 levels in the TSSC3 promoter region." (PMID 26265454, 2015). "We report the first dual EZH2-EHMT1/2 substrate competitive inhibitors and show that they may have greater activity in tumour cells that overexpress wild type EZH2." (PMID 26300989, 2015). "This novel PRC2 function in tumor cells could profoundly impact the mechanism of action and efficacy of EZH2 inhibitors in cancer treatment." (PMID 26030458, 2015). "In the present work, since EZH2 is abnormally up-regulated in eRMS, we sought to evaluate whether miR-101 might be altered in this tumor." (PMID 26251675, 2015). "Finally, many of the genes down-regulated by EZH2 GOF in this study that modulate ECM-adhesion/signaling display altered expression or have been ascribed roles in tumor biology (e.g. NRCAM, CEACAM1, SORCS1, ADAM23, MME)." (PMID 25671303, 2015). "The inhibition of the EZH2 expression or activity not only would prevent the changes in gene expression leading to tumor recurrence, but also could preclude tumor progression." (PMID 26517683, 2015). "Finally, the anti-tumor activity of etoposide in combination with the Ezh2 inhibitor DZNep was evaluated in vivo." (PMID 25605014, 2015).
tumor (continued). "Silencing of EZH2 resulted in tumor growth inhibition, apoptosis and chemosensitivity enhancement." (PMID 26265454, 2015). "Furthermore, honokiol treatment on T24 tumor xenografts confirmed its anticancer effects in vivo, including suppression tumor growth and tumor stemness, accompanied by the dysregulation of EZH2 and miR-143 expressions." (PMID 26484567, 2015). "To characterize the role of this SNP in neoplastic cells, we analyzed EZH2 rs3757441 in normal colonic tissue (as the SNP accounts for germline variation in gene sequence) and evaluated EZH2 expression in tumor cells by immunohistochemistry in a series of 119 primary CRC." (PMID 26553291, 2015). "Our results showed that EZH2 silencing down-regulated β-catenin, c-myc and cyclin D1, suggesting that the miR-506-EZH2 axis may suppress tumor proliferation and metastasis by inhibiting the Wnt/β-catenin pathway." (PMID 26452129, 2015). "Amplification or overexpression of EZH2 has been observed in a wide range of tumour types." (PMID 26300989, 2015). "Moreover, a recent preclinical study provided evidence for synergistic anti-tumor activity of the EZH2 inhibitor E7438 (EPZ-6438) and glucocorticoid receptor agonists in models of GCB-DLBCL in vitro." (PMID 26654227, 2015). "Thus, we studied the presence of H3K27me3 to understand the conflicting roles of EZH2 -- as either an oncogene or a tumor suppressor in different tumors." (PMID 26043758, 2015). "This evidence was confirmed by the induction of miR-101 expression also in tumor cells in which EZH2 was down-regulated through the treatment with DZNep, a compound which works inducing EZH2 degradation and already validated as an inhibitor of EZH2 by our group on the same context." (PMID 26251675, 2015). "Our results suggest that EZH2 may exert its oncogenic function partially by silencing tumor-suppressive miRNAs, and further research is required to fully characterize the miRNAs silenced by H3K27me3 in NSCLC." (PMID 26256448, 2015). "Notably, CBX2 and EZH2 were consistently the most highly overexpressed epigenetic regulators across multiple datasets from clinical and xenograft tumor tissues." (PMID 25859291, 2015). "Altogether, these results suggested a role of EZH2 silencing in tumor growth inhibition in vivo." (PMID 26265454, 2015). "EZH2 mediated tumor suppressor genes’ silencing contributes to cancer progression." (PMID 26378043, 2015). "Tumor suppressors such as DAB2IP have been reported as EZH2 or PRC2 targets." (PMID 25537508, 2015). "This scenario might suggest that, in these tumor cells, EZH2 must be depleted in order to allow miR-101 increase." (PMID 26251675, 2015). "To analyze the possible relationship between EZH2 and miR-200, we first characterized the expression of miR-200 members in our tumor series according the increased or reduced expression of EZH2 protein (also monitored by immunohistochemistry in tissue microarrays)." (PMID 26517683, 2015). "Gene knockdown of EZH2 reduces growth of a variety of tumour cell types." (PMID 26300989, 2015). "Moreover, down regulation of EZH2 expression by siRNAs or shRNAs has also been shown to inhibit cancer cell and tumor growth." (PMID 25520914, 2014). "Over-expression of EZH2 was involved in tumor initiation and progression." (PMID 25542019, 2014). "In various PCa cell lines, over-expression of miR-101, miR-26a and miR-26b could lead to repression of both EZH2 mRNA and protein as well as to a reduced cellular proliferation suggesting a tumor-suppressive function for these miRNAs in PCa." (PMID 24517338, 2014). "NSC745885 also suppressed tumor growth and down-regulated EZH2 in vivo." (PMID 25431950, 2014). "Moreover, the mean tumor weight at the end of the experiment was significantly lower in the sh-EZH2 group (0.213±0.066 g) compared with the empty vector group (0.655±0.231 g)." (PMID 24967960, 2014).
tumor (continued). "Inactivation of EZH2 inhibits metastasis, tumor angiogenesis and growth, and small molecule-mediated inhibition of the enzymatic function of Ezh2 may allow pharmacological treatment of cancer." (PMID 25359725, 2014). "In this study, we investigated the potential involvement of EZH2 in tumor angiogenesis of NPC." (PMID 25237831, 2014). "Given its role in tumor progression and stem cell maintenance, EZH2 or EZH2-mediated signaling may be attractive targets for potential cancer therapeutics." (PMID 25520914, 2014). "CAFs play a vital role in tumor initiation and progress and EZH2 expression in CAFs may also be essential though the detailed molecular mechanisms need to be clarified." (PMID 25025074, 2014). "By univariate and multivariate analysis, we observed low expression of EZH2 showed significant correlation with good tumor regression (p = 0.026) and down-staging (p = 0.021), which means EZH2 can reliably and independently predict the response to nCRT with LARC." (PMID 25159232, 2014). "Here we evaluate whether similar effects can be obtained also in the presence of growth factor-supplemented medium (GM), that mimics a pro-proliferative microenvironment, and by pharmacological targeting of EZH2 in RD cells and in RD tumor xenografts." (PMID 24575771, 2014). "A recent study demonstrated that the loss of EZH2, which is a part of polycomb repressor complex that catalyzes histone H3K27 methyltransferase, results in impaired pancreatic regeneration and accelerated KRasG12D-driven neoplasia." (PMID 24947474, 2014). "Aside from the transcriptional repression of tumor suppressor genes, EZH2 may contribute to tumor development by misleading of cells towards a stem cell-like status." (PMID 25431950, 2014). "Our study revealed that low EZH2 expression in biopsy tissue might be a useful predictive factor of good tumor response to nCRT and longer 5-year DFS in patients with LARC." (PMID 25159232, 2014). "The first evidence of the role of EZH2 as a main player in the inability of RMS cells to undergo differentiation has been recently reported in vitro for the embryonal RMS cell line RD, established from a tumor recurrence, through EZH2 genetic silencing upon serum withdrawal." (PMID 24575771, 2014). "In cancer cells, tumor-suppressor miRNAs are silenced by a repressive chromatin structure involving trimethylating histone H3 lysine 27 mediated by chromatin-modifying factors including EZH2." (PMID 24861464, 2014). "The EZH2-mediated H3K27 trimethylation may act as a platform to recruit DNMTs for aberrant CpG island hyper-methylation of promoters to silence tumor suppressor genes in cancers." (PMID 25431950, 2014). "Our data demonstrate that EZH2 down-regulation restores the myogenic differentiation of RD cells with no need to reduce serum (cultured in growth medium), and that pharmacological inhibition of EZH2 is a feasible way to restrain the tumor-promoting potential in embryonal RMS." (PMID 24575771, 2014). "Finally, to prove that aberrant inactivation of the ITGα2-cofilin axis, mediated by EZH2, increases tumour cell migration we measured migratory ability of HCT116, HCTshSUP, HCTshEZ-2 and DLD1 cells after ITGα2 silencing." (PMID 25549357, 2014). "Emerging evidence clearly indicates that EZH2 plays a crucial role in tumor angiogenesis." (PMID 25237831, 2014). "Overall, these results indicated that EZH2 promoted angiogenesis and tumor metastasis in vivo." (PMID 25237831, 2014). "Indeed, several reports have shown that genetic silencing and pharmacologic inhibition of EZH2 induced cell apoptosis, inhibited cell invasion and tumor angiogenesis, ultimately suppressed cancer growth and progression." (PMID 24345883, 2013).